DPP9 (dipeptidyl peptidase 9)
Diseases named in the same sentence as DPP9 in open-access papers (continued):
Sharing a sentence is not in itself a finding about the gene and the disease.
liver cancer (5 papers, 2021 to 2025). An epithelial or non-epithelial malignant neoplasm that arises from the liver. "Associations of DPP9 with human liver cancer, exonic single nucleotide polymorphisms (SNPs) in DPP9 and loss of function (LoF) variants have not been explored." (PMID 33915844, 2021). "Elevated DPP9 expression in liver cancer cells is associated with resistance to chemotherapy and poor outcomes, suggesting that targeting DPP9 could improve treatment efficacy." (PMID 39941813, 2025). "Another study showed that DPP9 gene loss-of-function exonic variants are linked to liver cancer." (PMID 39094401, 2024). "Since DPP9 significantly increases NRF2 protein levels in liver cancer cells, it can theoretically up-regulate the transcription of these downstream target genes as well." (PMID 39094401, 2024). "Dipeptidyl peptidase 9 (DPP9) is a member of the dipeptidyl peptidase IV family that has been found to be highly expressed in a variety of tumors, including liver cancer." (PMID 39094401, 2024). "In this study, we find that DPP9 weakens the responses of liver cancer cells to chemotherapy drugs by up-regulating NQO1 and inhibiting intracellular ROS levels." (PMID 39094401, 2024). "In this study, we find that DPP9 can inhibit ROS levels in liver cancer cells by up-regulating NQO1." (PMID 39094401, 2024). "Since DPP9 can regulate NQO1 in liver cancer cells, does DPP9 affect chemoresistance in liver cancer cells by regulating NQO1?" (PMID 39094401, 2024). "Collectively, our findings suggest that inhibiting DPP9/NQO1 signaling can serve as a potential therapeutic strategy for liver cancer." (PMID 39094401, 2024). "Next, we investigated the effect of DPP9 on NRF2 degradation in liver cancer cells and explored the related molecular mechanisms." (PMID 39094401, 2024). "The Dpp9 knockdown in liver cancer cells mediated the energy catabolism pathways by increasing the activation of AMPK, a regulator of anabolism." (PMID 36172198, 2022). "To further investigate DPP4 gene family expression in liver cancer prognosis, we stratified DPP9, DPP8 and DPP4 based on median expression in HCC." (PMID 33915844, 2021). "In the Huh7 liver cancer cell line, DPP9 activity is needed for DPP9 to influence cell migration." (PMID 40293537, 2025). "So, how does DPP9 regulate NRF2 protein levels in liver cancer cells?" (PMID 39094401, 2024). "Since we have shown that DPP9 can regulate the mRNA levels of NQO1 in liver cancer cells, the question arises as to whether DPP9 also has an impact on the protein stability of NQO1." (PMID 39094401, 2024). "However, RNA sequencing result shows that apart from NQO1 gene, there is no significant up-regulation observed for other NRF2 downstream target genes in liver cancer cells with DPP9 overexpression." (PMID 39094401, 2024). "Therefore, in this study, we focused on the effect of DPP9 on chemoresistance in liver cancer and explored related molecular mechanisms." (PMID 39094401, 2024). "Given DPP9's critical function in liver cancer, designing small-molecule inhibitors may offer a fresh method of treating this disease." (PMID 39094401, 2024). "Interestingly, we found that DPP9 could regulate ROS levels in liver cancer cells, and this regulatory effect was dependent on NQO1." (PMID 39094401, 2024). "It is unclear whether DPP9 affects chemoresistance in liver cancer." (PMID 39094401, 2024). "DPP9 and NQO1 protein levels in liver cancer and adjacent normal tissues were detected by using immunohistochemical (IHC) assay." (PMID 39094401, 2024). "However, it is unclear whether DPP9 may affect chemoresistance in liver cancer." (PMID 39094401, 2024). "To investigate which genes in liver cancer cells are regulated by DPP9, we performed RNA sequencing on SK-Hep-1 cells with and without DPP9 overexpression." (PMID 39094401, 2024). "The role of DPP9 in human liver cancer has not been studied, particularly in liver hepatocellular carcinoma (HCC)." (PMID 33915844, 2021).
liver cancer (continued). "This study reveals that DPP9 inhibits ubiquitin-mediated degradation of NRF2 protein by binding to KEAP1, up-regulates NRF2 protein levels, promotes mRNA transcription of NQO1, inhibits intracellular ROS levels, and thus weakens the responses of liver cancer to chemotherapy drugs." (PMID 39094401, 2024). "There was no discernible difference in the rate of NQO1 protein degradation in SK-Hep-1 and HepG2 cells following the overexpression and silencing of DPP9, indicating that DPP9 does not affect the levels of NQO1 protein in liver cancer cells by regulating the stability of NQO1 protein." (PMID 39094401, 2024). "DPP9 in human liver cancer cells (HepG2 and Huh7) could promote apoptosis and reduce proliferation by inhibiting the EGFR/PI3K/Akt signaling pathway, and inhibiting the expression and activity of DPP9 in Huh7 cells could decrease the adhesion and migration ability of cells." (PMID 36172198, 2022).
Obesity (5 papers, 2020 to 2024). Accumulation of substantial excess body fat. "Increased DPP9 expression was associated with obesity in HCC patients." (PMID 33915844, 2021).
oral squamous cell carcinoma (5 papers, 2021 to 2025). "DPP9 interacts with FAP directly in oral squamous cell carcinoma, and DPP9 overexpression can inhibit the epithelial-mesenchymal transition activity induced by FAP." (PMID 39876559, 2025). "In contrast, in patients with oral squamous cell carcinoma, lower DPP9 expression correlates with poor survival." (PMID 33915844, 2021). "However, overexpression of DPP9 in human oral squamous cell carcinoma (OSCC) cells could reduce cell migration, invasion, and adhesion." (PMID 36172198, 2022). "The knockdown of DPP9 in oral squamous cell carcinoma cells increased cell growth via FAP-α, whereas the overexpression of DPP9 in Huh-7 and HepG2 cells reduced proliferation and increased apoptosis independent of its enzymatic activity by interacting with HRAS." (PMID 37626841, 2023).
lung cancer (4 papers, 2021 to 2025). A malignant neoplasm involving the lung. "Uterine corpus endometrial carcinoma (UCEC) and lung carcinoma were the most common diagnosed cancers in patients with DPP9 LoF variants." (PMID 33915844, 2021). "DPP9 exonic LoF variants were most often associated with uterine carcinoma and lung carcinoma." (PMID 33915844, 2021). "One previous study showed that DPP9 knockdown can prevent the proliferation, migration, and invasion of lung cancer cells, and DPP9 overexpression is a significant independent predictor for poor 5-year overall survival in NSCLC patients." (PMID 39094401, 2024). "Our datamining evidence that DPP9 LoF was associated with lung carcinoma perhaps does not align with a previous study that linked high DPP9 mRNA expression with poor survival in human lung cancer." (PMID 33915844, 2021). "Supporting this concept, VbP (Talabostat; PT-100; BXCL-701), which exerts potent inhibition of DPP9 and DPP8 and moderate inhibition of DPP4 and FAP, has been shown to lessen tumor burden in lung cancer and sarcoma models." (PMID 33915844, 2021).
lung disease (4 papers, 2024 to 2026). "Examination of eQTL data from isolated cell types and lung disease states was necessary to reveal DPP9 and ATP11A as two additional causal genes." (PMID 39040187, 2024). "This review discussed potential applications of DPP9-selective inhibitors in treatments of cancer, viral infection, chronic inflammation, and lung diseases." (PMID 40293537, 2025). "This narrative review summarizes recent clinical and experimental evidence on the role of DPP-1, DPP-4, DPP-9, and DPP-10 in pulmonary diseases." (PMID 42193335, 2026).
viral infection (4 papers, 2021 to 2025). "It is tempting to speculate that DPP9 inhibition could alleviate other viral infections in which the virus remains dormant in the hosts’ cells, such as hepatitis B virus (HBV) or herpes simplex virus (HSV)." (PMID 40293537, 2025). "To date, no study has analysed the expression of DPP9 in tissues from the digestive system and peripheral leukocytes and the potential relationship with viral infection." (PMID 36358551, 2022). "Thus, DPP9 inhibition is beneficial in HIV therapy and potentially in other viral infections." (PMID 40293537, 2025). "However, recent studies have found that activation of human NLRP1 by both ZAKα/P38 axis following ribotoxic stress response and viral infection and by the ORF45 protein of the Kaposi's sarcoma‐associated herpesvirus are independent of DPP9." (PMID 37675820, 2023).
asthma (3 papers, 2021 to 2026). "In asthmatic patients carrying the NLRP1 variant M1184V (methionine 1,184 to valine), inhibition of DPP9 enzymatic activity reduces inflammasome activation, possibly exacerbating asthma." (PMID 36172198, 2022). "Combined with the in vitro data, this aligns with a causative effect of M1184V in asthma to decrease NLRP1 activation in the context of DPP9 inhibition." (PMID 33378691, 2021). "Collectively, this work defines the role of NLRP1 in asthma at a molecular level, and explains how the M1184V risk factor decreases activation in the context of DPP9 inhibition." (PMID 33378691, 2021). "Linking our in vitro and in vivo results, we found that the NLRP1 variant M1184V reduces inflammasome activation in the context of dipeptidyl peptidase 9 inhibition and could thereby increase asthma severity." (PMID 33378691, 2021). "Therefore, DPP8 and DPP9 may be involved in the occurrence and development of chronic inflammatory responses in asthma." (PMID 36172198, 2022).
colorectal cancer (3 papers, 2021 to 2025). A primary or metastatic malignant neoplasm that affects the colon or rectum. "Similarly, in colorectal cancer, greater DPP9 expression is associated with poor prognosis." (PMID 33915844, 2021).
colitis (2 papers, 2022). Inflammation of the colon. "DPP8 and DPP9 are more closely associated with gut inflammation and colitis." (PMID 36468400, 2022).
Ewing sarcoma (2 papers, 2013 to 2022). A small round cell tumor that lacks morphologic, immunohistochemical, and electron microscopic evidence of neuroectodermal differentiation. "DPP9 knockdown in Ewing sarcoma induced cell death through a regulation of cytokines such as poly, polymerase-1 and apoptosis-inducing factor." (PMID 35685372, 2022).
hepatocellular carcinoma (2 papers, 2021 to 2025). A malignant tumor that arises from hepatocytes. "Downregulating DPP9 or blocking its enzyme activity reduces cell adhesion and migration in the Huh7 human hepatoma cell line." (PMID 33915844, 2021).
multiple myeloma (2 papers, 2019 to 2021). "A DPP8 and DPP9 inhibitor can promote apoptosis by activating poly(ADP ribose) polymerase (PARP) and caspase-3 in multiple myelomas." (PMID 34359286, 2021).
prostate carcinoma (2 papers, 2017 to 2021). A carcinoma that arises from epithelial cells of the prostate gland. "The DPP9-rearrangements resulted in loss of the active sites of DPP9; it is well known that gene fusions may represent loss-of-function events which play a role in carcinogenesis, as reported in colorectal and prostate cancer." (PMID 28893231, 2017).
renal carcinoma (2 papers, 2022 to 2025). A carcinoma arising from the epithelium of the renal parenchyma or the renal pelvis. "DPP9 overexpression in renal cancer cells induced the expression of SLC7A11, which led to the protection of cells from ferroptosis." (PMID 39941813, 2025).
serous ovarian carcinoma (2 papers, 2017 to 2022). "We have found no studies describing fusions involving DPP9 in the Mitelman database or in the TCGA fusion gene portal; thus, this is the first report showing that DPP9-rearrangements occur in serous ovarian carcinoma." (PMID 28893231, 2017). "In high-grade serous ovarian cancer, DPP9 was involved in two gene rearrangements (rearrangement of DPP9 with PPP6R3 and DPP9 with PLIN3 respectively), and the expression of DPP9 3′ end was reduced, resulting in DPP9 losing the active domains." (PMID 36172198, 2022).
uterine corpus endometrial carcinoma (2 papers, 2021 to 2022). A endometrial carcinoma (disease) that involves the body of uterus. "Four DPP9 variants were designated as stop gained, with three of them associated with primary uterine corpus endometrial carcinoma (UCEC)." (PMID 33915844, 2021).
alcoholism (1 paper, 2021). "The intronic single nucleotide polymorphism (SNP) rs113683471 in DPP9 is associated with alcoholism." (PMID 33915844, 2021).
alopecia (1 paper, 2024). Hair loss usually from the scalp. "Selective DPP-8 and DPP-9 inhibitors were discovered in a rat toxicity study to be associated with severe toxicities leading to an enlarged spleen, multiorgan histopathological changes, and alopecia." (PMID 39177655, 2024).
breast tumor (1 paper, 2023). "In this study, we show that DPP8 and DPP9 play a pivotal role in maintaining autophagic flux and thereby contribute to the better survival of ER-/PR-positive breast tumor cells (luminal A)." (PMID 37626841, 2023).
Ewing Sarcoma Family of Tumor (1 paper, 2023). "In Ewing Sarcoma Family of Tumor (ESFT) cells, the knockdown of DPP4, DPP8, or DPP9 leads to NPY-mediated apoptosis." (PMID 37626841, 2023).
gynecological cancer (1 paper, 2021). "Together with the observation that low DPP9 expression was associated with poor survival in UCEC, it might suggest that DPP9 is a suppressor of gynecological cancer, which would align with the recently discovered role of DPP9 in BRCA2 homeostasis and DNA repair." (PMID 33915844, 2021).
immunotoxicity (1 paper, 2016). "DPP-8 and DPP-9 inhibition was reported to be associated with multiorgan toxicities and immunotoxicity in rats and dogs and attenuation of human T-cell activation in vitro in some, but not other studies." (PMID 27328054, 2016).
mastitis (1 paper, 2025). Inflammation of breast tissue during lactation or postpartum due to an obstructed duct or infection. "The DCTN1, MYOF, and DPP9 genes encode key regulators of intracellular transport, membrane repair, and protein degradation, respectively, and their expression changes driven by miR-223 suggest a comprehensive modulation of immune response and cellular resilience during mastitis." (PMID 40033327, 2025). "By regulating critical genes such as PTPRF, DCTN1, and DPP9, miR-223 emerges as a key molecular modulator that balances cellular processes, contributing to mastitis resistance and production traits like milk yield and fat content." (PMID 40033327, 2025). "The identification of DEGs and potential target genes, particularly PTPRF, DCTN1, PLEC, MYOF, and DPP9, underscores the critical role of miR-223 in modulating mastitis-related traits in dairy cattle." (PMID 40033327, 2025).
metabolic syndrome (1 paper, 2021). A cluster of metabolic risk factors for CARDIOVASCULAR DISEASES and TYPE 2 DIABETES MELLITUS. "Taken together, this information suggests that DPP9 has an important role in liver manifestations of the metabolic syndrome, which drives progression to NASH, fibrosis and HCC." (PMID 33915844, 2021).
metastatic colorectal cancer (1 paper, 2022). "DPP9 is also considered to be a poor prognostic factor for metastatic colorectal cancer, and inhibiting the activity or expression of DPP9 can inhibit the viability of tumor cells and increase the sensitivity to antitumor drugs." (PMID 36172198, 2022).
myeloid leukemia (1 paper, 2019). A clonal proliferation of myeloid cells and their precursors in the bone marrow, peripheral blood, and spleen. "Consistent with the requirement of a responsive Nlrp1b allele for efficient pyroptosis induction by DPP8/DPP9 inhibitors, 1G244 more potently induced cytotoxicity in the BALB/c-derived myeloid leukemia cell line J774.A1 than in the wild-type B6 primary macrophages." (PMID 30718379, 2019).
pneumonia (1 paper, 2023). An acute, acute and chronic, or chronic inflammation focally or diffusely affecting the lung parenchyma, caused by an infection in one or both of the lungs (by bacteria, viruses, fungi, or mycoplasma.). "Specifically, through a univariate regression analysis, we evaluated the association between risk allele carrier status for each genetic variant (OAS1/2/3, DPP9, IFNAR2, LZTFL1, ABO, and FUT2) and the development of clinical complications and of pneumonia." (PMID 36873632, 2023).
renal cell carcinoma (1 paper, 2025). "DPP9 KO in renal cell carcinoma 768-O cells led to the accumulation of ROS and decreased NRF2 induction by H2O2, but the effect was reversed by the expression of DPP9-WT, and not ΔESGE mutant, in DPP9 KO cells." (PMID 39941813, 2025).
serous carcinoma (1 paper, 2017). "DPP9 was found rearranged with PLIN3 in another serous carcinoma, and also in this case the DPP9 expression was disrupted and lowered toward the 3′ end." (PMID 28893231, 2017).
stomach adenocarcinoma (1 paper, 2021). "Another four DPP9 variants were designated as frameshift mutation, with half of them found in patients diagnosed with stomach adenocarcinoma." (PMID 33915844, 2021).